HMGA2 (high mobility group AT-hook 2)
Diseases named in the same sentence as HMGA2 in open-access papers (continued):
Sharing a sentence is not in itself a finding about the gene and the disease.
tumor (continued). "Notably, our results demonstrated that high HMGA2 overexpression and VM were both correlated with the tumour differentiation, stage, metastasis and poor prognosis (P < 0.05)." (PMID 28533522, 2017). "Furthermore, panobinostat is responsible for the up-regulation of hsa-let-7b, a tumor suppressor miRNA, and the consequent suppression of its target HMGA2." (PMID 27058414, 2016). "Many studies highlight the role of HMGA2 protein in cancer progression, HMGA2 protein levels in primary lung tumours has been shown to correlate with increasing tumour grade and has furthermore been regarded as a necessity for a transformed phenotype in metastatic NSCLC cell lines." (PMID 26858029, 2016). "Previous studies have proposed several mechanisms that may account for HMGA2 abilities to promote stem/progenitor cell self-renewal and tumor cell transformation." (PMID 27259253, 2016). "We wanted to gain more knowledge about the expression of HMGA2-related miRNAs such as miR-30c and let-7a, and whether a correlation exists between the expression of FHIT and HMGA2, in this tumor type." (PMID 27835588, 2016). "Let-7a is one of the most critical tumor suppressor miRNA that regulates HMGA2 expression." (PMID 26893968, 2016). "H19 promotes tumor cell migration and invasion by sponging let-7, thus relieving the inhibitory effect of let-7 on its targets, resulting in an increase of metastasis-promoting genes including Hmga2, c-Myc and Igf2bp3." (PMID 26623562, 2016). "The effects of classic clinicopathologic features, including age, gender, clinical stage, tumor stage (T stage), lymph node status (N status), distant metastasis, in conjunction with HMGA2 protein expression, on patient survival, were examined with Kaplan–Meier analysis and the log-rank test." (PMID 26818837, 2016). "Furthermore, IMP-3 ribonucleoproteins were demonstrated to operate as cytoplasmic safe houses that kept HMGA2 mRNA from miRNA-directed decay during tumor progression." (PMID 26796627, 2016). "Up-regulated genes EGFR and HMGA2 are possible tumor markers of OSCC." (PMID 26179909, 2015). "Recently, it has been reported that treatment of TNBC-derived cell lines and primary mouse tumor cells with small molecule inhibitor ICG-001 blocks proliferation in TNBC cells through down-regulating expression of HMGA2, a regulator of stem cell self-renewal, proliferation and differentiation." (PMID 25658419, 2015). "HMGA2 is widely considered as a driver of tumor metastasis and a switching actor of EMT." (PMID 25884389, 2015). "Variant rs12423095 in HMGA2 showed a moderate association with tumor size in AA only although no significant heterogeneity was observed between AA and EA, possibly indicating a spurious association due to the low minor allele frequency at this SNP." (PMID 26236334, 2015). "Interestingly, both overexpression of let-7a3 and let-7b and knockdown of HMGA2 resulted in decreased cell proliferation and colony formation in a rhabdoid tumour cell line, emphasizing the role of these microRNAs in cells selected under stem cell conditions." (PMID 26064134, 2015). "In aggregate, these data suggest that HMGA1 and HMGA2 are expressed in non-overlapping tumor types, but are both associated with more aggressive phenotypes, and perhaps reduced patient survival." (PMID 26244988, 2015). "These miRNAs are tumor suppressors by targeting oncogenes including Ras, HMGA2 and MYC." (PMID 26244871, 2015). "All cases found positive for HMGA2 mRNA in the plasma showed HMGA2 expression at the tumor level." (PMID 25749380, 2015). "Tumor-marker genes (HMGA2, TPD52, and GPC5) were overexpressed in U3-C and U3-DT." (PMID 25978455, 2015). "HMGA2 could potentially serve as tumour marker in both species while HMGA1 might play a minor role in OSCC progression." (PMID 25245141, 2014).
tumor (continued). "Here, an inverse correlation of the expression of HMGA2 and Lin28 and let-7a and mir-98 could be detected in the tumour samples when compared to healthy tissue." (PMID 25245141, 2014). "The balance of let-7 and HMGA2 is discussed to play a major role in tumour aetiology." (PMID 24914948, 2014). "Moreover, the disrupted pairing between let-7 and HMGA2 by mRNA truncations of the 3′UTR was reported to induce HMGA2 overexpression leading to tumor formation." (PMID 25276782, 2014). "We analyzed 10 tumor samples of HMGA2 transgenic animals and no mutation were found (data not shown)." (PMID 25014774, 2014). "Based on the preceding experiments, we hypothesized that one potential function of HMGA2 in Wnt10b-driven tumours is the control of proliferation." (PMID 23307470, 2013). "In this study we have identified HMGA2 as the most highly expressed gene in Wnt10b-driven tumours." (PMID 23307470, 2013). "We next validated the expression of HMGA2 by IHC in Wnt10bLacZ-driven tumours." (PMID 23307470, 2013). "There is strong expression of HMGA2 protein levels in most of the Wnt10bLacZ-driven tumours cells." (PMID 23307470, 2013). "The HMGA2 gene is involved in mesenchymal cell differentiation and tumor formation." (PMID 23860207, 2013). "Moreover, the expression of miR-98 was positively correlated with RKIP relative expression and negatively correlated with HMGA2 in tumor tissues." (PMID 24392454, 2013). "Several recurrent, albeit infrequent, genetic aberrations have been observed in these tumours, including deletions in chromosome 7q, trisomy of chromosome 12, various rearrangements affecting the high mobility group AT-hook 2 (HMGA2) gene, and structural changes at 6p21." (PMID 23132392, 2012). "Via protein-DNA binding HMGA2 plays important roles in tumor growth and stem cell-renewal." (PMID 21533145, 2011). "To determine whether the reduction in tumor growth displayed by let-7a-expressing tumor cells may be at least in part mediated by the concomitant decrease in HMGA2 expression, we used an shRNA approach to deplete HMGA2 expression in A673 and TC252 cells." (PMID 21853155, 2011). "HMGA2 amplification was more common in C5 tumours (p = 0.005, Mann-Whitney test)." (PMID 21533284, 2011). "Therefore, while HMGA2 amplification is more common in C5 tumours, amplification-independent mechanism(s) must account for C5-specific over-expression of mRNA and protein." (PMID 21533284, 2011). "Similarly, in more differentiated tumour cells, let-7 is expressed at higher levels, and its target oncogenes (HMGA2 and ras) are downregulated." (PMID 20179807, 2010). "Unfortunately, we could not observe the clear inverse correlation between the expression of let-7 and HMGA2 protein expression, although high expression of HMGA2 was frequently detected in tumours with significant downregulation of let-7 (42%)." (PMID 19156147, 2009). "The altered form of the HMGA2 gene, on the other hand, could somehow be related to the generation of human benign and malignant tumours." (PMID 14647145, 2003). "In addition, the expression of HMGA2 was upregulated in OSCC tumor tissues." (PMID 40900300, 2025).
tumor (continued). "Similarly, the tumor suppressor let-7-5p family members play an important modulatory role in multiple human cancers including HCC by repressing oncogenic targets such as EGFR/LIN28B/ HMGA2 and C-MYC that are all important players in oncogenesis." (PMID 38256049, 2024). "Furthermore, a distinctly higher level of HMGA2 protein was also found in clinical tumor samples." (PMID 38845972, 2024). "Therefore, targeting HMGA2 for the regulation of EMT may be an important strategy for combating tumor metastasis, recurrence, and drug resistance." (PMID 38361784, 2024). "HMGA2 overexpression may foster the tumor progression and DTX resistance in the PCa cells." (PMID 38361751, 2024). "In addition, HMGA2, a tumour derivative, could up‐regulate the gene transcription of CCL2 in tumour‐associated macrophages (TAMs) by regulating the STAT3 signalling pathway." (PMID 36872292, 2023). "Importantly, based on our data for 7 Ba/Sq samples, we were able to identify higher enhancer activity associated with potential key genes in Basal tumour biology, including cell surface receptors (IL7R, OSMR, EGFR, MET) and transcriptional regulators (BNC2, HMGA2, KLF7, NR3C1)." (PMID 36944729, 2023). "However, how HMGA2 affects the tumor microenvironment is unclear." (PMID 35388172, 2022). "Mice bearing Hmga2 knockout MC38 tumors showed decreased infiltrating CD11b+F4/80+ macrophages and CD11b+F4/80+CD206+ M2 macrophages, indicating that anti-tumor effects of Hmga2 depletion might involve mechanisms mediated by the recruitment and polarization of TAMs in CRC." (PMID 34976223, 2022). "The HMGA2 protein might be a valuable prognostic marker for predicting tumor recurrence." (PMID 36568211, 2022). "There are data suggesting that HMGA2 may regulate angiogenesis in tumor formation." (PMID 33668453, 2021). "Overall, our study suggests that knockdown of RhoC expression is able to suppress the malignant biological behavior of OSCC, specifically the malignant properties of cell invasion, migration, tumor growth, and lymph node metastasis, and these might be achieved by regulating HMGA2 expression." (PMID 33519932, 2021). "In detail, HMGA2 expression was linked to better survival in triple negative breast cancer and well-differentiated estrogen receptor-positive breast cancer patients irrespective of lymph node metastases or tumor size." (PMID 34302528, 2021). "Furthermore, circFBXL5, miR-216b and HMGA2 abundances were detected in tumor tissues." (PMID 34281530, 2021). "Certain miRNA also functions as tumor suppressors, for instance, the let 7 family suppresses tumor development and metastasis via targeting key oncogenic genes like high-mobility group AT-hook 2 (HMGA2), members of the RAS family (NRAS, KRAS, and HRAS), and MYC." (PMID 35145899, 2021). "In fact, HMGA2 differential expression has been mainly, but not exclusively, associated with squamous tumors, being its expression related with several aspects of tumor evolution, particularly, invasion and metastasis." (PMID 31737655, 2019). "Finally, we found that LBH589, an HDAC inhibitor, inhibited the proliferation of NF1 MPNST cells through HMGA2 and may thus be used as a targeted drug to control this tumour." (PMID 31053152, 2019). "We aimed to determine whether HMGA2 regulates tumour growth through MSI2." (PMID 31053152, 2019). "Thus, HMGA2 reduces the sensitivity of tumor cells toward PARP inhibitors." (PMID 30289618, 2019). "Besides HMGA2, miR-302a or miR-367-3p may target multiple genes and pathways to inhibit tumour growth and metastasis." (PMID 29391048, 2018). "Also, the HMGA2 can inhibit tumor cell apoptosis by protecting the telomere." (PMID 29487700, 2018). "We found the level of HMGA2 was positively associated with TNM stage, tumor differentiation, tumor invasion depth, lymph node metastasis, lymphovascular invasion, and vascular invasion, which indicated that HMGA2 might have a significant relationship with advanced features of cancer." (PMID 29997523, 2018).
tumor (continued). "Besides, High HMGA2 expression in tumor cells correlate with tumor differentiation P=0.007." (PMID 29245924, 2017). "Further studies are necessary to find out whether myolipomas of soft tissue in any systematic way differ from the other tumor types in the exact manner in which HMGA2 is abrogated, in particular whether fusion with C9orf92 is a general feature of these rare neoplasms." (PMID 26857357, 2016). "In conclusion, our study highlights a pivotal role for miR-543 as a tumor suppressor in the regulation of CRC cell proliferation and metastasis by targeting KRAS, MTA1 and HMGA2 and suggests that miR-543 may serve as a novel diagnostic and prognostic biomarker for CRC metastasis." (PMID 26968810, 2016). "In order to determine whether Src association with the HMGA2 and SMYD3 promoters is maintained in the patients’ tumors in vivo, we performed ChIP on samples derived from formalin-fixed paraffin embedded (FFPE) tumor blocks utilizing the newly developed PAT-ChIP method." (PMID 26695438, 2016). "This study suggests that HMGA2 may play a pivotal role in tumor metastasis and can be a novel diagnostic marker and potential therapeutic target in TSCC." (PMID 26818837, 2016). "Thus, strong TRIM71 activity potentially suppresses cellular transformation driven by Lin28B-let-7 in tumors in which this pathway is conserved by attenuating Lin28B protein function, thereby inhibiting tumor cell growth through inhibition of potential let-7 target oncogenes, especially HMGA2." (PMID 27821801, 2016). "In addition, this tumor had focal amplification of HMGA2 and MET genes." (PMID 26275293, 2015). "Thus, the tumour suppressor function of caspase 2 may become a new option in therapeutic strategy aimed at control of tumour growth under a high level expression of HMGA2." (PMID 25300915, 2015). "Therefore the influencing parameters on the achieved perforation rate and cell viability were systematically determined and the successful transfection of cells with a fluorescent siRNA as well as the knock down of the oncogene HMGA2 in tumor cells with specific siRNAs was demonstrated." (PMID 25645721, 2015). "To verify that the reduction of tumor growth associated with let-7a expression was HMGA2-dependent, we performed a rescue experiment where the cDNA encoding HMGA2 lacking its endogenous 3′ UTR was expressed in A673 and TC252 cells prior to their infection with the let-7a-expressing retrovirus." (PMID 21853155, 2011). "The significant involvement of HMGA2 in the epithelial–mesenchymal transformation of PSC and PPS, driving tumour stemness, as well as its crucial role in chemotherapy resistance, necessitates further investigation into the underlying mechanism of action." (PMID 41469334, 2026). "High mobility group proteins (HMGA1, HMGA2, HMGB1) and miR-106a-5p are involved in tumor progression, but their interplay in UC remains incompletely understood." (PMID 41828319, 2026). "In our functional enrichment analysis, we identified several common interacting protein-coding genes within the IGF2BPs gene family including IGF2, HMGA2, and LIN28A/B, all of which are known to facilitate tumor progression." (PMID 40088376, 2025). "The combination of HMGA2 inhibitors and targeted macrophage immunotherapy (CD47 monoclonal antibody) had the better tumor suppression effect." (PMID 40703517, 2025). "We used IF for the basal PDAC phenotype marker, HMGA2, and the classical marker, Galectin-4 (GAL4), to assess tumor phenotypes semiquantitatively." (PMID 41006303, 2025). "We found that the expression of 9 DE-ceRNAs were significantly different between tumor tissues and normal tissues, including the upregulated H19, HOTAIR, miR222, miR148a, PCDHGB4, GMNC and HMGA2 and the downregulated LRP2 and MBP in tumors." (PMID 40351420, 2025).
tumor (continued). "Let-7 also acts as a tumor suppressor by directly targeting oncogenes such as RAS, HMGA2, and c-Myc." (PMID 41226664, 2025). "We also detected the expression of CCNA2 and HMGA2 by IHC stating assay in CDX and PDX model tumor tissues and found that the knockdown of 6PGD decreased the expression of CCNA2 and HMGA2 proteins." (PMID 40611205, 2025). "Compact tumor organoids exhibited a higher expression of genes involved in WNT-mediated maintenance of nephron progenitors (e.g. LGR5, MYCN, HMGA2, LIN28B, NCAM, WNT4, BMP7)." (PMID 39740515, 2025). "By inhibiting the expression of hsa_circ_0005325 in OSCC tumor tissues, the expression of miR‐433‐3p in SCC25 and CAL‐27 cells was inhibited, and in another group, the expression of HMGA2 in SCC25 and CAL‐27 cells was promoted." (PMID 40900300, 2025). "The overexpression of HMGA2 in CRC cells promoted macrophage recruitment and M2 polarization by upregulating STAT3-mediated CCL2 secretion, thereby promoting tumor immune suppression in CRC." (PMID 40703517, 2025). "Whereas the HMGA2::MSRB3 and HMGA2::FHIT fusions were described in previous studies, the remaining detected fusion partners such as ARID2 or IFNG-AS1 are novel in this tumor type." (PMID 40033554, 2025). "In addition, the HMGA2 protein also stimulates the TGF-β, MAPK, and PI3K signaling pathways, which in turn increases HMGA2 expression within a positive feedback loop, causing a significant increase in HMGA2 levels as the tumor reaches the stage of muscle invasion." (PMID 40204943, 2025). "Oncogenic markers GPC3, HMGA2, and TNFRSF19 are dramatically increased in the tumor section of HBL116." (PMID 39796711, 2024). "Based on the TCGA database, the patients were divided into two groups (Tumor group and Normal group), of which 56 cases were normal controls, and high expressions were also observed on CLDN10, HMGA2, and LAMB3." (PMID 39205691, 2024). "For instance, tumor sample CCGA-UBC-034T contained an ecDNA with seven genes, including CDK4, DDIT3, GLI1, HMGA2, PTPN11, RFC5, and TMPO." (PMID 39267784, 2024). "The authors showed that binding of miR-142-3p to the 3′ non-coding region (3′UTR) in HMGA1, HMGA2, HMGB1, and HMGB3 mRNAs leads to apoptosis of tumor cells, as well as to decreased proliferation, migration, and invasion." (PMID 39062899, 2024). "Data demonstrated that HMGA2 can regulate the TGFβ/SMAD and MAPK signaling pathways to induce tumor cell invasion and migration." (PMID 38361784, 2024). "In this model, logistic regression analyses demonstrated that clinical parameters (age, gender, and tumor stage) and core molecules (SLC2A1, TLE1, FAM83A, HMGA2, FBXO44, and MTRNR2L12) contributed differently to LUAD scores at different stages." (PMID 38338834, 2024). "These dual roles of HMGA2 in BER and replication fork stabilization highlight its critical contribution to maintaining genomic integrity in highly proliferating tumor cells." (PMID 39085703, 2024). "In addition, considering that the correlation trends of circTHSD4, miR-203 and HMGA2 were relatively weak in PCa tumor samples, a larger size of clinical samples could provide more convincing conclusion regarding the expression pattern of these molecules in PCa cells." (PMID 38361751, 2024). "By promoting efficient base lesion repair and stabilizing stalled replication forks, HMGA2 helps to prevent DNA damage accumulation and DSB formation, thereby contributing to tumor cell survival and progression." (PMID 39085703, 2024). "In the future, these mice will be very useful to extend our in vitro observations and to characterize the roles of miR-204-5p and HMGA2 in the MAPK signalling pathway and more precisely in the control that this pathway exerts on tumor progression and invasion." (PMID 37445942, 2023). "Group 3 and Group 4 show higher expression of Hmga2, which has been reported to regulate EMT programs during tumor progression 7,11,15,16." (PMID 36993454, 2023).